GZMB (granzyme B)
Diseases named in the same sentence as GZMB in open-access papers (continued):
Sharing a sentence is not in itself a finding about the gene and the disease.
tumor (continued). "We further analyzed the tumor supernatants of tumors treated with Th2 cells compared to control and found soluble GZMB and FAS to be increased." (PMID 36376448, 2023). "This was further evidenced by the immunohistochemical staining, where both CD8 and granzyme B, which play a critical role in cytotoxic T-cell-mediated antitumor immunity, were overexpressed in tumor tissues treated with COF-919 + 660 + 808 nm." (PMID 37660063, 2023). "The results showed that high IERS was associated with high tumor purity, high activated CD4 memory cells, M0 and M1 macrophage abundance, high PD-L1, CXCL10, and GZMB expression." (PMID 36936970, 2023). "The depletion of Tregs in mice bearing lung AC (LUAD) treated with anti-CD25-depleting mAb restrained lung tumor growth and enhanced the recruitment of CD8+ T cells, leading to the upregulation of granzyme A, granzyme B, perforin, and tumor cell death." (PMID 36776832, 2023). "Considering that TRAIL and its corresponding receptor, TRAIL receptor, induce apoptosis in tumor cells, this suggests an alternative apoptotic pathway independent from granzyme B and perforin pathways." (PMID 38077321, 2023). "It is possible that high granzyme B expression creates selection pressure for tumor cells to escape antitumoral host responses." (PMID 37894418, 2023). "GZMB plays an important role in T cell- and NK cell-mediated tumor killing and can predict tumor immunotherapy response, which high expression in NK and T cells of the responding population." (PMID 37152010, 2023). "The incremental tumor cell death is attributed to the shear-induced activation of NK cells, which then deliver more granzyme B into CTCs to induce apoptosis, while the roles of the secreted cytokines and death ligands are dispensable." (PMID 37575881, 2023). "IL12-MSA upregulated CD25 expression in TdLNs, spleens, and tumors of KP.SIY flank tumor–bearing mice and spleens of KP.SIY lung tumor–bearing mice, while GzmB levels were only increased in the TdLNs of KP.SIY flank tumor–bearing mice." (PMID 37669107, 2023). "In HBV-related HCC, cytotoxic CD4+ T cells present similar numbers with cytotoxic CD8+ T cells, while they are less effective to eliminate tumor cells due to secreting less cytolytic factors such as granzyme A (GzmA) and granzyme B (GzmB)." (PMID 38090482, 2023). "One of the most significantly upregulated proteins in the tumor periphery was granzyme B. Validation experiments showed intertumoral heterogeneity of granzyme B upregulation." (PMID 37894418, 2023). "NK-exos have been reported to contain cytotoxic proteins known to induce apoptosis (e.g., perforin and granzyme B) and to exert anti-tumor effects in various cancer cells." (PMID 37484408, 2023). "A study showed that combining A2AR antagonist SCH58261 with anti-PD-1 antibody improved CAR-T-cell function and upregulated granzyme B expression in tumor-infiltrating CD8 + T cells." (PMID 38201467, 2023). "(G) Expression of markers of degranulation (CD107a) and cytotoxicity (Granzyme B) in tumor infiltrating CD8+ T cells." (PMID 36883731, 2023). "Reduced MHC-I expression and poor infiltration by CD8+, Granzyme B+ T cells were observed in tumor regions where Tregs and mast cells co-localize each other, with such features associated with resistance to anti-PD-1 treatment." (PMID 37492581, 2023). "B cells can promote anti-tumour immunity through the release of cytokines such as IL-12, IFNγ, granzyme B and TRAIL57." (PMID 37365284, 2023). "VPS4B codes for a protein that is involved in autophagy that can reduce the sensitivity of T cell-mediated tumor cell lysis by lowering granzyme B content, and it is an essential factor required for escaping CD8+ T cell-mediated killing in tumors." (PMID 36936916, 2023). "In the tumor microenvironment, secreted GZMB enters cancer cells by a perforin-dependent mechanism and activates cascades leading to apoptosis." (PMID 37553332, 2023).
tumor (continued). "NK EVs with higher levels of perforin and granzyme B have been reported to have more potent anti-tumor activity than EVs with lower amounts, suggesting that these proteins are primary mediators of cell death." (PMID 38201518, 2023). "Formulations encapsulating granzyme B showed a clear tumour growth inhibition and improved median survival rates of the mice, compared to non-functionalised polymersomes." (PMID 36537575, 2023). "By examining the levels of effector molecules (CD69, CD107a, GZMA, IFN-γ, TNF-α, GZMB, and Perforin-1), we also noticed that the tumor-infiltrating CD8+ T cell effector response was significantly enhanced by Rig-I deficiency." (PMID 36927693, 2023). "The authors demonstrated that GzmB cleavage led to nanoparticle disassembly and turn-on fluorescence emission, allowing in vivo imaging of active GzmB in tumor-bearing mice." (PMID 37376918, 2023). "To further verify this notion, we examined CD68, IL‐1β, CD8, and granzyme B, a cytotoxic executor, in clinical tumor tissues of HG‐SOC patients with fluorescence multiplex immunohistochemical analysis." (PMID 37009412, 2023). "We also found that infiltration of granzyme B‐positive cells was increased in the tumor tissues of the mice treated with anti‐GM2 7 × 19 CAR‐T cells compared to those with Conv." (PMID 37031457, 2023). "TLR3 ligand poly A:U shifts the immunosuppressive tumor microenvironment towards anti-tumor immunity by altering the composition in favor of antigen-specific CD8+ granzyme B+ T cells, resulting in a lower Treg/CD8+ cell ratio." (PMID 37936697, 2023). "Consistent with increased granzyme B levels in circulating CD8+ T cells after therapy, granzyme B expression in CD431B11+ tumor-infiltrating CD8+ T cells was increased by PDOX treatment." (PMID 36796366, 2023). "Both HER2-CAR-NK cells and sPD-1-CAR-NK cells promoted NK cell infiltration into the tumor tissue and increased release of granzyme B, and sPD-1-CAR-NK cells displayed more potential than HER2-CAR-NK cells." (PMID 37047817, 2023). "Tumor-derived Tregs mediate immunosuppressive effects by expressing granzyme B and perforin to induce apoptosis of effector T and NK cells." (PMID 37936703, 2023). "In the level of NKs’ functional state, autophagy inducesattenuation of the anti-neoplastic effect of these cells via degrading granzyme B, which is enclosed in their granules and has a pivotal lytic effect against tumor cells." (PMID 36833401, 2023). "Combined DSF and programmed cell death protein 1 (PD-1) antibody treatment markedly increased the number of granzyme B (GZMB)-positive CD8+ T cells in the tumor." (PMID 37326784, 2023). "Meanwhile, IFN-γ and granzyme B were detected, which are secreted by tumor-infiltrating T cells and play an important role in tumor inhibition." (PMID 36635683, 2023). "IFNγ acts together with granzyme B and perforin to initiate apoptosis in tumor cells but also enables the synthesis of immune checkpoint inhibitory molecules, such as PD-L1, thus stimulating other immune-suppressive mechanisms." (PMID 38003396, 2023). "Activated MAIT cells secreted high levels of effector molecules such as IFN-γ, granzyme B, and perforin, which in turn led to a significant tumor-suppressing immune response." (PMID 36463401, 2023). "(B) As in A with quantification of expression of markers of degranulation (CD107a) and cytotoxicity (Granzyme B) in tumor infiltrating CD8+ T cells." (PMID 36883731, 2023). "T cells were found to kill tumor cells in a granzyme B or Fas-FasL-dependent manner during co-culture, and the co-cultured T cells exhibited markers of tissue-resident memory phenotype." (PMID 37016422, 2023). "Activated effector CD8+ T cells that recognize tumor antigens can attack and eradicate tumor cells through perforin and granzyme B-mediated cytolysis, Fas/FasL pathway activation, and/or cytokine release (such as IFN-γ and TNF-α)." (PMID 37766136, 2023).
tumor (continued). "The data showed that NKG2D-CAR-NK92 cells with GPR116 receptor knockdown released more cytotoxic substances such as GzmB and IFNγ, and suppressed tumor growth more effectively both in vitro and in vivo compared to NKG2D-CAR-NK92 cells." (PMID 36895027, 2023). "Mechanistically, NK and CD8 T cytotoxic lymphocytes deliver granzyme B (GzmB) into GSDME-expressing tumor cells, where GzmB cuts GSDME to induce pyroptosis." (PMID 36742298, 2023). "Flow cytometry analysis showed the increase in IFNγ- and granzyme B (Gzmb)-secreting tumor-infiltrating T cells by TAS-115 treatment." (PMID 37258621, 2023). "While CD8 T cells from different groups of tumor-bearing mice expressed comparable levels of perforin, Granzyme B and CD107a, PD1 expression appeared to be reduced in mice treated with FGK, which is consistent with previous findings." (PMID 37291146, 2023). "TIL-Bs have various antitumor immune mechanisms, including producing tumor-specific antibodies and inducing antibody-dependent cellular cytotoxicity, inducing tumor apoptosis through granzyme B production, and acting as antigen-presenting cells." (PMID 37476181, 2023). "In conclusion, we have shown that zinc exerts its tumor-suppressive effect by acting on T cells, the center of cellular immunity, and increases the transcription of granzyme B, one of the key molecules in tumor immunity." (PMID 37298408, 2023). "These NK cells were able to lyse tumor cells because they upregulate their transcription and release of granzyme B (GZMB) and interferon-gamma (IFN-γ)." (PMID 37131214, 2023). "Once activated T lymphocytes arrive at tumor tissues, they can release cytotoxic substances such as perforin and granzyme B to eliminate tumor cells." (PMID 36849442, 2023). "The activation of GSDME and caspase-3 through cleavage by Granzyme B leads to pyroptosis of tumor cells by NK cells, CD8+ killer lymphocytes, and chimeric antibody receptor T cells." (PMID 37077542, 2023). "The degranulation markers CD107a and Granzyme B were analyzed on the CD8+ cytotoxic T subpopulation after co-culturing with the tumor cells." (PMID 37349298, 2023). "Subsequent analyses showed production of IFNγ and GzmB- and Perforin-dependent killing of tumor cells by tgTCR CD4+ T cells in a MHC class II-dependent manner." (PMID 37965314, 2023). "NK EVs with higher levels of perforin and granzyme B have been shown to have more potent anti-tumor activity than EVs with lower amounts, suggesting that these proteins are critical mediators of cell death." (PMID 37818374, 2023). "Tumor derived HSP70/bag-4 surface positive exosomes can stimulate NK cells to release granzyme B, which in turn triggers tumor cell apoptosis." (PMID 37823027, 2023). "Consistently, an increased number of infiltrated CD8+ T cells and stronger granzyme B signals were detected in the tumor sections isolated from 6J1‐treated mice implanted with Rab27‐knockdown 4T1 cells, when compared with those from other groups." (PMID 36567273, 2023). "Cell surface-bound human Hsp70 (hHsp70) sensitises tumour cells to the cytolytic attack of natural killer (NK) cells through the mediation of apoptosis-inducing serine protease, granzyme B (GrB)." (PMID 37074531, 2023). "The density of tumor-infiltrating CD11c+ DCs and GzmB+CD8+ T cells was markedly decreased in the OXP/CU-CPT22 group." (PMID 37945630, 2023). "Conversely, compared to tumor front granulocytes, stromal granulocytes expressed higher levels of granzyme B and Ki67." (PMID 38125025, 2023). "Donors of Vγ9Vδ2 T cells with the highest co-occurrence of granzyme B and perforin show the most efficient killing of tumour cells." (PMID 37758698, 2023). "Of note, the stroma of PF patients harbored significantly higher numbers of proliferating cytotoxic GZMB+ and Treg cells compared with the tumor area." (PMID 37349318, 2023).
tumor (continued). "It enhanced the release of immune effector cytokines (IFN-γ, TNF-α, GZMB) in both peripheral and tumor tissue and suppressed Treg cells to improve tumor immunosuppression." (PMID 37397393, 2023). "Upregulation of IFNγ and granzyme B suggest these cells can directly engage and kill tumor cells in the TME." (PMID 37965337, 2023). "As an essential effector of antitumor immunity, cytotoxic lymphocytes require granzyme B (GB) to eliminate tumor cells through granule-mediated apoptosis, and GB expression levels reflect the cytotoxic activity of CD8+ T lymphocytes." (PMID 37340461, 2023). "Caspases cascade activation plays a central role in perforin/granzyme B-induced apoptosis in tumor cells." (PMID 37511553, 2023). "Activated NK cells, which express HSP70 receptors such as the C-type lectin receptors CD94/NKG2C and NKG2D, bind to membrane HSP70 on tumour cells and secrete granzyme B, either alone or in combination with perforin, leading to cell death." (PMID 37446252, 2023). "It is likely that tumor subtype, activation status of other immune cells and molecular expression on B cells jointly determine the role of GzmB+ B cells in antitumor immunity." (PMID 37215990, 2023). "There was a significant (p < 0.05) increase in the percentage of CD8+ T cells, as well as a significant (p < 0.01) increase in IFN-γ and granzyme B secretion in tumours receiving US+CA+aPD-L1." (PMID 37631324, 2023). "In recurrent tumors, binding was still observed, suggesting that antigen escape was not the mechanism of recurrence; rather, there was upregulation of immunosuppressive factors, specifically PD-L1, on tumor cells and decreased GzmB positivity of CAR T cells." (PMID 37754534, 2023). "It acts as a cytotoxic cytokine and, with granzyme B and perforin, initiates apoptosis in tumor cells." (PMID 37298519, 2023). "Granzyme B (GrzB) is an extremely high anti-tumor bioactive protein produced mainly by CD8+ T cells and NK cells." (PMID 36674931, 2023). "Fn significantly reduced the αPD-L1-mediated increase in CD4+CD3+ and CD8a+CD3+ cells and the activity (GZMB+) of the infiltrated CD8a+ T-cell population in the tumor region." (PMID 37723150, 2023). "Ex vivo killing assays demonstrated an ability of these cells to directly kill tumor cells as well as express granzyme B and TRAIL." (PMID 37965337, 2023). "Consistently, tumor‐infiltrating CD8+ T cells in an IL‐21R knockout mouse model exhibited inhibited granzyme B (GZMB) production." (PMID 37829505, 2023). "Subsequently, to assess how IL‐1β blockade reshaped the TIME, we determined the levels of PD‐L1, F4/80, and granzyme B in ID8 tumor tissues with IHC staining." (PMID 37009412, 2023). "CD94 on NK cells interacts with membrane Hsp70 on tumor cells, induces granzyme B production and release, and thereby induces tumor cell apoptosis." (PMID 37238744, 2023). "Activated neutrophils have been described to kill tumor cells directly via induction of ROS and granzyme B." (PMID 37317970, 2023). "For instance, exosomes produced by NK cells contain elements like GzmA, perforin, GzmB, granulysin, and FasL, which can exert cytotoxic effects on tumor cells." (PMID 37892995, 2023). "OT-I cells with effector-like phenotypes showed greater accumulation in glutamine-treated tumours, and also showed increased T-bet expression and higher frequencies of granzyme B- or IFNγ- and TNF-co-expressing cells." (PMID 37407815, 2023). "Although they are not exhausted NK cells, the resting phenotype is less competent in tumor eradication and contain less granzyme B and perforin granules." (PMID 38071322, 2023). "Along with enhanced IFN-γ production, absence of PD-1 signaling also displayed a significantly enhanced expression of otherwise repressed Eomes, granzyme B and CD107a expression, correlating well with enhanced cytotoxic activity and anti-tumor potential." (PMID 37205114, 2023).
tumor (continued). "Flow cytometry analysis showed that PV-1 increased the numbers of CD8+ tumor-infiltrating lymphocytes (TILs) and increased the production of granzyme B, TNF-α, and IFN-γ by CD8+ TILs." (PMID 38077406, 2023). "Mechanistically, TH-302 NPs reduced the expression of HIF-1α and PD-L1, facilitated the infiltration of CD8+ T cells and increased the levels of TNF-α, IFN-γ, and granzyme B in tumours, thereby enhancing the efficacy of α-PD-1 therapy." (PMID 37993847, 2023). "Of note, the observed increase in abundance of tumor-infiltrating granzyme B-expressing CD8+ T cells is consistent with the phenotype previously reported for Ptpn2-null B16F10 tumors." (PMID 36968224, 2023). "The cytotoxicity of NK cells involves secretion of cytotoxic granules containing the pore-forming protein perforin and procaspase-cleaving granzyme B (GzmB), which induces apoptosis in targeted tumor cells." (PMID 38264648, 2023). "The expression of IFN-γ and granzyme B (GzmB) was also higher in the 3D cultured group in the micropore-forming hydrogel, which enhanced the cytotoxicity of NK cells and the extinction of the tumor." (PMID 37349810, 2023). "The results elucidated that the patients with high expression of ISG15 showed positive staining for Granzyme B and Perforin, indicating that the lymphocytes had stronger killing effect on tumor cells." (PMID 37217923, 2023). "Conversely, the prevalence of CD8+ T cells that express Granzyme B+ and Ki67+ was notably greater within the tumor stroma of HPV+ patients compared to HPV− patients." (PMID 38019346, 2023). "Autophagy inhibition by targeting Beclin1 or Atg5 restored granzyme B levels in hypoxic cells in vitro and induced tumor regression in vivo facilitating NK-mediated tumor cell killing." (PMID 38071322, 2023). "Granzyme B (GrB) is the most abundant serine protease in the granules of cytotoxic T-cells and natural killer cells, mediating anti-tumor immunity." (PMID 36890824, 2023). "A PET imaging agent targeting a functional marker of effector T cell activation, granzyme B, allows for direct quantification of anti-tumor response before changes in tumor volume." (PMID 36828374, 2023). "We wanted to study effector CD8+ T cells in the tumor area, including granzyme B released by T cells." (PMID 38093288, 2023). "GALNT10 encodes for polypeptide N-acetylgalactosaminyltransferase 10, which is associated with the increased regulatory CD4+ T cell infiltration and decreased granzyme B expression in CD8+ T cells in tumor tissues." (PMID 36609529, 2023). "The correlation between granzyme B upregulation in the tumor periphery and patient survival suggests local selection pressure for aggressive tumor growth and disease progression." (PMID 37894418, 2023). "Similar to previous studies, anti‐PD‐1 therapy greatly enhanced tumor infiltration, including increased accumulation of T cells expressing the effector molecules granzyme B and IFN‐γ." (PMID 37946697, 2023). "Mannose-6-phosphate receptors on the surface of tumor cells are upregulated after treatment with certain chemotherapeutic agents, making it easier for granzyme B released by cytotoxic T lymphocytes (CTLs) to penetrate tumor cells and self-regulate." (PMID 36979400, 2023). "In this study, we have shown that zinc exerts its tumor-suppressive effect by acting on cytotoxic T cells, the center of cellular immunity, and increases the transcription of granzyme B, one of the key molecules in tumor immunity." (PMID 37298408, 2023). "Chemotherapy is found to sensitize the tumor cells by releasing granzyme B, which helps CAR-T cells to gain easy access to the antigens of cancer cells." (PMID 38201467, 2023). "The results showed that tumor inhibition positively correlated with CD8, granzyme B, and F4/80, but was inversely linked with TGF-β1 in tumor tissues." (PMID 36765611, 2023).